CD80 (CD80 molecule)
Diseases named in the same sentence as CD80 in open-access papers (continued):
Sharing a sentence is not in itself a finding about the gene and the disease.
head and neck cancer (5 papers, 2021 to 2024). A primary or metastatic malignant neoplasm affecting the head and neck. "Among genes potentially responsible for OSCC-GB progression, upregulation of immune checkpoint genes—CD274, CD80, and IDO1—was also observed in head and neck cancer patients." (PMID 33980865, 2021). "Another study confirmed that the keratinocyte line expressing MHC II has the characteristics of the absence of CD80 and CD86 in head and neck cancer, which may be a way for tumors to evade immune surveillance." (PMID 36230722, 2022).
hepatocellular carcinoma (5 papers, 2009 to 2023). A malignant tumor that arises from hepatocytes. "We selected inducible T cell costimulator (ICOS) rs4404254 T>C, rs10932029 T>C, CD28 rs3116496 T>C and CD80 rs7628626 C>A SNPs and assessed the potential relationship of these SNPs with hepatocellular carcinoma (HCC) risk." (PMID 31235485, 2019). "We have reported that the supernatant from human hepatocellular carcinoma (HCC) cells induced functional impairment of DCs as demonstrated by the downregulation of MHC class I and class II, CD80, CD86, and CD83 molecules." (PMID 20182533, 2009).
multiple sclerosis (5 papers, 2014 to 2024). A progressive autoimmune disorder affecting the central nervous system resulting in demyelination. "For example, a recent report demonstrated that B cells from patients with multiple sclerosis exhibited decreased Dicer expression that resulted in enhanced expression of CD80, suggesting Dicer may be pertinent in immune cell function in certain disease states." (PMID 27356752, 2016). "Subsequently, some studies have found that CD80+ B cells can be used as a possible therapeutic target for HTLV-1-related myelopathy/tropical spastic paraparesis and multiple sclerosis." (PMID 39575257, 2024). "Although CD80 and CD86 costimulatory molecules play prominent roles in immune regulation and reflect disease status in multiple sclerosis (MS), data in HAM/TSP are lacking." (PMID 24472094, 2014).
periodontitis (5 papers, 2021 to 2026). An acute or chronic inflammatory process that affects the tissues that surround and support the teeth. "Periodontitis influences the serum levels of CTLA-4, which in turn alters the T cell activation pathways, PD-1 pathways, and CD80 activation, which has a key role in antigen presentation and implicates the B cell-mediated antibody response in periodontitis." (PMID 41395347, 2025). "A disruption in CD80/CD163 balance seems to be related to the pathogenesis of periodontitis and peri-implantitis, being less prominent in the latter." (PMID 36286036, 2022). "Within the limitations of this study, the CD80/CD163 balance seems to be disrupted in periodontitis and peri-implantitis." (PMID 36286036, 2022). "An increased CD80/CD163 or CD80/CD206 ratio was also expected from peri-implantitis lesions when compared to periodontitis, due to prior research demonstrating that M1 polarization occurs more prominently in peri-implantitis lesions." (PMID 36286036, 2022). "We found the CD80/CD206 ratio to be similar across groups, while a disrupted CD80/CD163 balance was observed in patients with periodontitis, possibly corresponding to the increasing pro- to anti-inflammatory macrophage ratios." (PMID 36286036, 2022). "Between-group comparisons revealed lower CD163 levels (p = 0.004) and a higher CD80/CD163 ratio (p = 0.002) in the periodontitis group than in the periodontally healthy group." (PMID 36286036, 2022). "CD163 levels were found to be decreased (p = 0.004), and the CD80/CD163 ratio was found to be elevated (p = 0.002) in periodontitis lesions compared to healthy gingiva." (PMID 36286036, 2022). "Because a higher intensity of CD80 expression was demonstrated in diseased sites than healthy sites of the same patients with periodontitis, we hypothesized that CD80 levels should increase in periodontitis, which was rejected." (PMID 36286036, 2022). "The present study demonstrates an increased CD80/CD163 ratio and decreased CD163 protein levels in tissues affected by periodontitis when compared to healthy gingiva." (PMID 36286036, 2022). "The more pronounced elevation of the CD80/CD163 ratio and decrease of CD163 levels in periodontitis lesions indicate different immune characteristics in periodontal and peri-implant lesions." (PMID 36286036, 2022). "For instance, no change in CD80 expression level on B cells was reported in periodontitis lesions, while a downregulation occurs in CD80 expression on epithelial cells upon challenge with various bacteria and lipopolysaccharides." (PMID 36286036, 2022). "Finally, a thorough description of CD80, CD163, and CD206 levels, and their ratios in the oral fluids of periodontitis and peri-implantitis patients, may allow them to be considered as early markers of these diseases." (PMID 36286036, 2022). "No statistical difference was observed in CD163 levels and CD80/CD163 ratio between the periodontitis and peri-implantitis groups (p = 0.402, p = 0.270, respectively) or between the periodontal health and peri-implant health groups (p = 0.594, p = 0.859, respectively)." (PMID 36286036, 2022). "Therefore, the aim of this study was to compare CD80, CD163, and CD206 levels and their ratios in soft tissue samples of periodontitis, peri-implantitis, clinically healthy gingiva, and clinically healthy peri-implant mucosa, irrespective of the number of cells expressing them." (PMID 36286036, 2022).
pulmonary fibrosis (5 papers, 2017 to 2025). Chronic progressive interstitial lung disorder characterized by the replacement of the lung tissue by connective tissue, leading to progressive dyspnea, respiratory failure, or right heart failure. "In this way, we next evaluated the profile of lung macrophages during the inflammatory phase of BLM-induced lung fibrosis, studying the cell surface expression of CD80 and MHCII as pro-inflammatory-associated molecules and CD206 as an anti-inflammatory by flow cytometry." (PMID 36766744, 2023). "Our studies have shown increased deposition of collagen with silica-induced pulmonary fibrosis, which is concurrent with the increased percentage of the CD11b+CD11c+ subset of CFPs expressing CD80/CD86, suggesting that DDR2/collagen I signaling may play a role in activation of the immune CFP subset." (PMID 28700752, 2017). "Notably, despite the elevated expression of M2 macrophage markers in the lungs of mice with pulmonary fibrosis, the elevated levels of dimeric iNOS, CD80, and COX-2 implied that chronic pulmonary inflammation might persist in the pathogenesis of pulmonary fibrosis." (PMID 38259493, 2023). "This study showed that, in the early stages of BLM-induced pulmonary fibrosis (5 days), AM express higher levels of CD206 and CD80 than the vehicle control, while, in later stages (21 days), AM only express higher levels of CD206 than the vehicle control." (PMID 36766744, 2023). "Furthermore, our findings highlighted aberrant expression of dimeric iNOS, CD80, and COX-2 proteins, along with the Nos2 gene in the lung tissue of mice with BLM-induced pulmonary fibrosis." (PMID 38259493, 2023). "On the other hand, these data do not suggest a clearly defined IM phenotype since CD80, and CD206 expression levels slightly decrease throughout the inflammatory phase of BLM-induced pulmonary fibrosis." (PMID 36766744, 2023).
sarcoma (5 papers, 2021 to 2024). A usually aggressive malignant neoplasm of the soft tissue or bone. "To further characterize the influence of HDACi on sarcoma cells, we evaluated changes in the expression of surface markers including CD80, HLA-ABC and PD-L1 on SW982 cells." (PMID 35203582, 2022). "Equivalent expression of CD80 could be observed between HDACi pretreated sarcoma cells and the DMSO control." (PMID 35203582, 2022). "Specifically, in sarcoma, the expression level of SMC4 is significantly correlated with monocyte markers CD14 and CSF1R, TAM marker CD80, and M1 macrophage marker PTGS2." (PMID 36719264, 2023). "Sunitinib treatment induced a significant upregulation of co-stimulation molecules CD80 and CD86 in both sarcoma cell lines (p < 0.01 and p < 0.0001, respectively) when compared to DCs loaded with untreated sarcoma cells." (PMID 33717062, 2021).
adenoma (4 papers, 2016 to 2021). A neoplasm arising from the epithelium. "The microarray data set (Geo dataset GSE15960) showed a significant up-regulation of CD80 expression in adenoma derived CEC vs normal mucosa derived CEC as well as vs carcinoma derived CEC." (PMID 31072360, 2019). "CD80 mRNA levels were inversely correlated with the DNMT3A mRNA levels in healthy colonic mucosa of patients with adenoma and with DNMT3B in healthy colonic mucosa of patients with cancer (τ = −0.44, p = 0.07 and τ = −0.50, p = 0.04, respectively)." (PMID 27377375, 2016). "Recent studies suggest that CD80 expression is upregulated in human colonic epithelial cells isolated from preneoplastic adenomas, while in skin SCC, a population of Cancer Stem Cells (CSCs) that express CD80 have been reported in both murine and human tumors." (PMID 31959281, 2020). "To address this question, we compared CD80 expression on colonic epithelial cells (CEC) isolated from normal human colonic mucosa, preneoplastic (i.e. adenoma) and neoplastic (i.e. adenocarcinoma) specimens." (PMID 31072360, 2019).
breast tumor (4 papers, 2017 to 2023). "Therefore, up-regulation of CD80 may indicate T cell tolerance in the breast tumor microenvironment, CD80 has the potential to be used as a CD80/CD86–CTLA4 pathway blocking therapy." (PMID 26942414, 2017). "Furthermore, staining wild-type or GRP78 heterozygous breast tumors with CD68 (green) and CD80 (red) indicates that GRP78 heterozygousity increases the CD68+/CD80+ double positive cell infiltration into the breast tumor, suggesting an elevated tumoral M1-like macrophage population." (PMID 29113324, 2017).
brucellosis (4 papers, 2008 to 2021). Brucellosis is a bacterial infection that spreads from animals to people via unpasteurized dairy products or by exposure to contaminated animal products or infected animals. "When westudied CD80/CD28 costimulation in human brucellosis, it was indicatedthat heat-killed B.abortus (HKBA) significantly downregulated the PHA-induced increase ofCD80+ monocytes." (PMID 19190764, 2008). "We have previously shown that heat-killed B. abortus (HKBA) can downregulate the PHA-induced increase of CD4+/CD25+ and CD14+/CD80+ cells of brucellosis patients." (PMID 19190764, 2008). "Regarding the frequency of CD14+monocytes expressing CD80 costimulation molecule, a significant increase wasfound in both of brucellosis groups in comparison to “cured” (P = .002 and .001,resp)." (PMID 19190764, 2008). "Previously,we stimulated PHA-cultured PBMCs from brucellosis patients with HKBA in orderto investigate any possible effect of brucellar antigen/s (mainly LPS) on theexpression of CD25 and CD80/CD28 costimulation molecules." (PMID 19190764, 2008). "In vivo, IL-6, TNF-α, and CD80/CD86 are required for activation of the interferon gamma-producing CD4+ Th1 and CD8+ cytotoxic T cells, a protective response induced by the host against brucellosis." (PMID 34992597, 2021). "In vivo, IL-6, TNF-α, and CD80/CD86 are required in the activation of the interferon gamma-producing T CD4+ helper type 1 (Th1) and T CD8+ cytotoxic, a protective response induced by the host against brucellosis." (PMID 32765455, 2020). "Moreover, 3-MA restored CD80 and CD86 expression levels on M1 macrophages, and CD163 and CD206 expression levels on M2 macrophages in brucellosis patients." (PMID 28659924, 2017). "E.coli addition in PHA cultures did not further enhance the increase in thepercentage of CD14+/CD80+ monocytes in both groups of brucellosis patients." (PMID 19190764, 2008). "Specifically, inchronic brucellosis patients, high percentage of CD14+/CD80+ monocytes in PHAand PHA plus E. coli LPS cultures might compensate for an ineffectualCD4+ T-cell response characterizing these form of disease." (PMID 19190764, 2008).
Burkitt lymphoma (4 papers, 2020 to 2024). A rare form of malignant mature B-cell non-Hodgkin lymphoma. "To establish a range of target cells for our experiments, we analyzed the surface expression of CD80 and CD86 on four DLBCL and one Burkitt lymphoma cell line." (PMID 38340727, 2024).
Chagas disease (4 papers, 2018 to 2022). A parasitic infection caused by Trypanosoma cruzi. "In Chagas disease, it was observed that there was a higher frequency of CD80+ monocytes in IND and CARD patients and a lower frequency of CD86+ monocytes only in the CARD form." (PMID 35665256, 2022). "As detailed above, patients with the IND clinical form of Chagas disease show a higher expression of CD86 than CD80 co-stimulatory molecules by all monocyte subsets." (PMID 29599775, 2018). "In addition, we evaluated the main cytokines produced by total CD4+ T cells after anti-CD80 or anti-CD86 antibody blockade from PBMC cultures of Chagas disease patients and healthy individuals." (PMID 35665256, 2022). "However, little is known about monocytes subsets in Chagas disease and the influence of CD80 and CD86 co-stimulatory expression in the modulation of the immune response in Chagas patients." (PMID 29599775, 2018). "Although the role of CD80 and CD86 co-stimulatory molecules is already known to activate adaptive immunity, the involvement of these molecules in Chagas disease is poorly studied." (PMID 35665256, 2022). "Using flow cytometry, we evaluated the effect of in vitro stimulation with Trypanosoma cruzi antigens on the expression of the co-stimulatory molecules CD80 and CD86 in different monocyte subsets of patients with IND and CARD clinical forms of Chagas disease." (PMID 29599775, 2018). "CD80 and CD86 co-stimulatory molecules in monocytes from patients with Chagas disease following induction by T. cruzi recombinant antigens are important for the activation of T cells." (PMID 29599775, 2018). "Through comparing the proportion of CD28 and CTLA-4 ligands in each lymphocyte subsets between patients with Chagas disease, we observed a higher proportion of CD28 on CD8+ Treg cells only after anti-CD80 blockade from CARD in comparison with anti-CD86 blockade and to IND group." (PMID 35665256, 2022). "Many studies have demonstrated the functional role of CD80, CD86, CTLA-4, and CD28 receptors in different pathological settings, yet little is known about the role of these co-stimulatory molecules in Chagas disease patients." (PMID 30405039, 2018). "Ultimately, we aimed to characterize the functional-phenotypic profile of monocyte subsets and understand the CD80/CD86 co-stimulatory expression by monocyte subsets in the protective and/or regulatory immunity against T. cruzi infection to further understand Chagas disease progression." (PMID 29599775, 2018). "Thus, using monoclonal blocking antibody for CD80 and CD86 receptors, we assessed the functional phenotypic profile of CD4+ T and CD8+ T lymphocytes and their subsets from cultures of PBMC after TRYPO stimulation from healthy and Chagas disease patients." (PMID 35665256, 2022). "We demonstrated that CD80 and CD86 receptors have different functions in lymphocytes activation from patients with Chagas disease, and CD80 may be responsible for the modulation of Treg lymphocytes activation in patients with CARD, pointing out a key molecule in the development of cardiomyopathy." (PMID 35665256, 2022).
chronic kidney disease (4 papers, 2021 to 2024). Impairment of the renal function secondary to chronic kidney damage persisting for three or more months. "As proteinuria, albuminuria, and CD80 levels also decreased, the authors hypothesize that the podocytes were protected by a reduction in CD80 overexpression, which led to a general improvement in their condition and a reduction of the risk of progressive chronic renal failure." (PMID 38255680, 2023).
eosinophilia (4 papers, 2007 to 2023). "Eosinophilia in curcumin-treated mice was markedly reduced, co-stimulatory molecule expression (CD80, CD86, and OX40L) on antigen-presenting cells was decreased, and expression of MMP-9, OAT, and TSLP genes was also attenuated." (PMID 17254346, 2007). "Regarding in vivo models, a previous study showed that intranasal administration of anti-CD86 mAb markedly reduced AHR, IgE production, and airway eosinophilia in OVA-sensitized/challenged mice whereas the treatment with anti-CD80 reduced airway eosinophilia alone." (PMID 25344652, 2014).
esophageal cancer (4 papers, 2018 to 2022). A primary or metastatic malignant neoplasm involving the esophagus. "Moreover, our study indicates that EBV and cytomegalovirus elevate PD-L1 or PD-L2, CD80, CD86, PD-1, CTLA-4, Tim-3, LAG3, and 4-1BB expression in multiple cancers along the gastrointestinal tract including stomach and esophageal carcinoma and colon and rectum adenocarcinoma." (PMID 30911684, 2019).
experimental autoimmune encephalomyelitis (4 papers, 2014 to 2024). An autoimmune demyelinating disease of the central nervous system that is produced experimentally in animals by the injection of homogenized brain or spinal cord in Freund's adjuvant. "Increased expression of co-stimulatory molecules has usually been associated with an immune activating phenotype of APCs, but recently expression of B7 (CD80/CD86) on murine B cells was shown to be central to regulation of CD4+CD25high Tregs in experimental autoimmune encephalomyelitis." (PMID 25401487, 2014).
gastric adenocarcinoma (4 papers, 2019 to 2023). "Thus, it is important to consider that the CD80 gene is differentially expressed in gastric adenocarcinoma cell lines." (PMID 37765273, 2023). "Besides PD-L1, PD-L2, PD-1, CD80, CD86, CTLA-4, Tim-3, LAG3, and 4-1BB, we found the increase of an inducible co-stimulator (ICOS) expression in both HPV-positive head and neck squamous cell carcinoma and EBV-positive stomach adenocarcinoma tumors." (PMID 30911684, 2019).
HCMV infection (4 papers, 2015 to 2024). "Remarkably, for both types of SmyleDC, the frequency of CD80+ cells initially increased upon HCMV infection (80%), being maintained at constant level in SmyleDCpp65 for 10 days." (PMID 26052526, 2015). "While CD83 surface expression was significantly reduced (p < 0.001), CD80 and HLA-DR were not influenced by HCMV infection." (PMID 28203230, 2017).
parasite infection (4 papers, 2015 to 2024). "In contrast, CD86 blockade or dual blockade of CD80 and CD86 resulted in the inability of mice to clear parasitemia to sub-patent levels." (PMID 30631323, 2018). "DCs recruited to the peritoneum also showed an up-regulation of the co-stimulatory molecules CD80 and CD86, suggesting that these DCs acquire a semi-mature phenotype upon parasite infection." (PMID 26720149, 2015). "Since the CD80-PD-L2-CD73+ B cell population was elevated during the primary PyNL infection and persisted at 1-M post-parasitemia clearance, we assessed whether the immune CD73+ B cell population could protect against a PyNL infection by adoptive transfer." (PMID 32886698, 2020).
thymoma (4 papers, 2014 to 2026). A neoplasm arising from the epithelial cells of the thymus. "To this end, we introduced human CD1d and CD80 into the murine thymoma cell line BW5147 (BW)." (PMID 31092850, 2019). "DAC has been shown to induce tumor-specific CTLs in a murine tumor model via upregulation of CD80 on the thymoma cell line EL4, resulting in enhanced immunological co-stimulation via CD80, increased CTL infiltration of tumors, and ultimately tumor rejection after DAC treatment of mice." (PMID 28359286, 2017).